CIMAP3 (ciliary microtubule associated protein 3)
Description:
During primary cilia disassembly, involved in cilia disassembly. Required specifically to control cilia retraction as well as the liberation and duplication of the basal body/centrosome. May act by stimulating AURKA activity at the basal body in a cell cycle-dependent manner.
Synonyms: C1orf88; PIFO; FLJ23853; pitchfork
Tractability: No criterion of Open Targets' tractability assessment is met for any kind of drug.
Gene: Protein-coding gene on chromosome 1 (111,346,600 to 111,353,013, forward strand). Ensembl gene ENSG00000173947.
Subcellular location: Cytoplasmic vesicle; Golgi apparatus, trans-Golgi network; Cytoplasm
Subcellular location (Human Protein Atlas): Vesicles
Gene Ontology:
Molecular function: beta-tubulin binding; gamma-tubulin binding; kinesin binding; protein binding; protein kinase binding; small GTPase binding; cytoskeletal protein binding
Biological process: positive regulation of kinase activity; regulation of cell projection organization
Cellular component: ciliary basal body; cytoplasm; cytoplasmic vesicle; trans-Golgi network; Golgi apparatus; nucleus
Genetic constraint (gnomAD): Loss-of-function variants: 17 observed, 21.87 expected, observed/expected ratio (o/e) 0.78, 90% interval 0.53 to 1.17. The upper end of that interval is the gene's LOEUF score, 1.17, which puts it in group 5 of 6, group 1 being the genes least tolerant of losing a copy. Missense variants: 199 observed, 217.5 expected, observed/expected ratio (o/e) 0.91, 90% interval 0.81 to 1.03. Synonymous variants: 69 observed, 74.64 expected, observed/expected ratio (o/e) 0.92, 90% interval 0.76 to 1.13.
Homologues: Orthologues: chimpanzee CIMAP3 (98% identical), macaque CIMAP3 (95% identical), guinea pig CIMAP3 (73% identical), rabbit CIMAP3 (73% identical), mouse Cimap3 (66% identical), rat Cimap3 (65% identical), tropical clawed frog cimap3 (45% identical), zebrafish si:ch211-66i15.4 (43% identical).
Diseases named in the same sentence as CIMAP3 in open-access papers:
CIMAP3 is named in the same sentence as 3 diseases in open-access papers, as found by Europe PMC text mining. Sharing a sentence is not in itself a finding about the gene and the disease.
CIMAP3 shares sentences with these, for which no sentence is quoted: tumor (4 papers); cancer (2); cardiovascular disease (1).